OAS1 (2'-5'-oligoadenylate synthetase 1)
Diseases named in the same sentence as OAS1 in open-access papers (continued):
Sharing a sentence is not in itself a finding about the gene and the disease.
lung adenocarcinoma (5 papers, 2021 to 2025). A carcinoma that arises from the lung and is characterized by the presence of malignant glandular epithelial cells. "OAS1 overexpression influenced survival and immune cell infiltration in patients with lung adenocarcinoma and OAS2 was shown to participate in a sustained senescence response of human primary melanocytes upon repeated UVB exposure." (PMID 40312750, 2025). "A previous study showed that lung adenocarcinoma (A549) cells constitutively expressed OAS1 and OAS3 mRNA." (PMID 34099596, 2021). "We found that overexpression of ZNF71 in A549 lung adenocarcinoma cells resulted in the downregulation of multiple components of the intracellular intrinsic and innate immune systems, including dsRNA (OAS1) and dsDNA (STING, pTBK1) sensors and viral restriction factors (TRIM5, SAMDH1)." (PMID 36499305, 2022). "Furthermore, overexpression of OAS1 affects survival in lung adenocarcinoma (LUAD) patients and immune cell infiltration, suggesting it may serve as a potential prognostic marker for LUAD." (PMID 41584451, 2025).
Obesity (5 papers, 2008 to 2024). Accumulation of substantial excess body fat. "Patients under 65 years old showed a higher expression of TFRC (p = 0.002), CCL5 (p < 0.001) and IFI6 (p = 0.006), and those with obesity (BMI ≥ 30) presented higher expression of OAS1 (p = 0.008) and TGFB1 (p = 0.008)." (PMID 38731851, 2024). "A number of host factors including SNPs of interferons IL28A, IL28B, IL29, interferon-γ, MBL, IL -10, IL-18, CTLA4, TRAIL, TGF-β, MX1, Osteopontin, LMP7, OAS1 genes, insulin resistance, obesity and ethnicity, have been found to modulate the treatment response." (PMID 24079723, 2013). "As observed with bulk RNA-sequencing, we observed a global suppression of interferon signaling pathways with pregravid obesity across all clusters as exemplified by reduced expression of interferon-stimulated genes (IFIT3, ISG15, OAS1)." (PMID 34195568, 2021). "Our study shows a higher expression of OAS1 and TGFB1 in individuals with obesity." (PMID 38731851, 2024).
pneumonia (5 papers, 2017 to 2024). An acute, acute and chronic, or chronic inflammation focally or diffusely affecting the lung parenchyma, caused by an infection in one or both of the lungs (by bacteria, viruses, fungi, or mycoplasma.). "The association was also confirmed comparing OAS1/2/3 variant frequency in the children cohort with pneumonia to that of the control cohort (OR 3.2; 95% CI 1.08–9.4; p-value 0.035)." (PMID 36873632, 2023). "The OAS1/2/3 risk variant was the main genetic risk factor for pneumonia development [Odds ratio (OR) 3.28, 95% CI 1-10.7; p value 0.049]." (PMID 36873632, 2023). "Specifically, through a univariate regression analysis, we evaluated the association between risk allele carrier status for each genetic variant (OAS1/2/3, DPP9, IFNAR2, LZTFL1, ABO, and FUT2) and the development of clinical complications and of pneumonia." (PMID 36873632, 2023). "The level of OAS1 is directly related to hospitalization frequency in cases of diagnosed pneumonia." (PMID 37896870, 2023). "Therefore, OAS1/2/3 variation, tagged by rs10735079, was associated with increased risk for pneumonia, independent of other genetic or clinical risk factors." (PMID 36873632, 2023).
SARS-CoV infection (5 papers, 2006 to 2023). "rs2660 in the 3’ UTR of OAS1 has been previously associated with SARS-CoV infection, being the genotypes A/G and G/G protective." (PMID 37809329, 2023). "In conclusion, we showed that the SNPs in OAS1 and MxA genes were associated with SARS-CoV infection in Chinese Han population." (PMID 16824203, 2006). "Our findings indicate that the G allele in the OAS1 gene conferred protection against SARS-CoV infection." (PMID 16824203, 2006). "The frequency “GA” and “GG” genotypes of rs1131454 (OAS-1; G > A) were also found to be higher in 44 Vietnamese severe acute respiratory syndrome (SARS) patients (Controls n = 153; SARS positive n = 44)." (PMID 36833454, 2023). "Among the antiviral proteins induced by IFN1, 2'-5' oligoadenylate synthetase 1 (OAS1) and myxovirus resistance 1 (MxA) harbour genetic variants that might affect susceptibility to the SARS-CoV infection and progression." (PMID 32917282, 2020).
colorectal cancer (4 papers, 2022 to 2025). A primary or metastatic malignant neoplasm that affects the colon or rectum. "The identification of BET1L and OAS1 as novel loci associated with colorectal cancer (CRC) in East Asian populations provides significant insights into the disease’s pathogenesis." (PMID 40303978, 2025). "The association of OAS1 with both colorectal cancer and cardiovascular diseases such as angina pectoris underscores the potential role of chronic inflammation and immune dysregulation as common mechanisms underlying these conditions." (PMID 40303978, 2025). "Colocalization analysis confirmed that the association signals at BET1L and OAS1 were shared between colorectal cancer and colon polyps, supporting a common genetic basis for adenoma progression to malignancy." (PMID 40303978, 2025). "Among these, BET1L and OAS1 were previously unreported in colorectal cancer studies, while BMP2 had been identified in European populations, highlighting both novel and shared genetic risk factors across ancestries." (PMID 40303978, 2025). "In contrast, studies on other cancer types, such as lung and colorectal cancer, have observed OAS gene mutations, particularly in OAS1 and OAS2, though these alterations are relatively rare." (PMID 39633486, 2024). "Notably, dysregulation of OAS1 expression has been observed in several cancers, including colorectal cancer, where it may influence tumor progression by modulating the immune microenvironment." (PMID 40303978, 2025). "(D) Colorectal cancer (CRC) tissue mRNA levels of IFI27 and OAS1 were determined by qRT-PCR, and (E) their relationships with VPS9D1-AS1 were calculated with Pearson correlation analysis." (PMID 36458816, 2022). "Collectively, these findings highlight the importance of metabolic and immune pathways in the pathogenesis of colorectal cancer and suggest that BET1L and OAS1 could serve as potential biomarkers or therapeutic targets." (PMID 40303978, 2025).
hepatoma (4 papers, 2013 to 2024). "In agreement with the previous reports, IFN-αinduced expression of ISGs, such as of Mx1 and OAS1, in the chicken hepatoma cells required HDAC activity." (PMID 24068929, 2013). "In hepatocellular carcinoma (HCC), OAS family genes, particularly OAS1 and OAS2, play a role in the tumor immune response." (PMID 39633486, 2024). "To this end, we compared the expression of twelve genes either linked to the induction of innate immunity (STAT1, STAT2, PKR) or IFN effector genes (OAS1/2, IFIT1–3, RSAD2, MX1, TRIM14, ISG15) in HCV-infected hepatoma cells and mature iHLCs." (PMID 29497123, 2018).
lung carcinoma (4 papers, 2017 to 2023). "We next tested the ability of the same four 18 bp dsRNAs to activate the OAS1/RNase L pathway in human lung carcinoma A549 cells as assessed by RNase L-mediated rRNA cleavage." (PMID 32678884, 2020). "We found that OAS1, ACE2, TMPRSS2 were associated with overall survival of lung cancer." (PMID 35082790, 2021). "Our microarray data analysis revealed and RT-qPCR confirmed the increased mRNA expression of all of the OAS gene family members (OAS1, OAS2, OAS3, OASL) and XAF1 and IRF7 in the lung cancer cell line A549 after transfection with BNC2." (PMID 28184177, 2017).
psoriasis (4 papers, 2019 to 2025). An autoimmune condition characterized by red, well-delineated plaques with silvery scales that are usually on the extensor surfaces and scalp. "What's more, the use of biological agents suppressed the serum OAS2 and OAS3 at low levels and elevated the serum OAS1 level in patients with psoriasis." (PMID 38298734, 2024). "The role of the OAS1 gene has been implicated in the cell cycle-dependent proliferation of epidermal keratinocytes and the induction of type I IFN via control of the Jak/STAT pathway in psoriasis." (PMID 40100809, 2025). "In addition, the use of biological agents suppressed the serum OAS2 and OAS3 and elevated the serum OAS1 level in psoriasis patients." (PMID 38298734, 2024). "Thus, serum markers of psoriasis patients using different biologics, including OAS1, OAS2, and OAS3, were also tested." (PMID 38298734, 2024). "Additionally, the utilization of biological agents resulted in the suppression of serum OAS2 and OAS3 at low levels, along with an elevation in the serum OAS1 level among patients with psoriasis." (PMID 38298734, 2024). "In addition, the use of biological agents may suppress the serum OAS2 and OAS3 at low levels and elevate the serum OAS1 level in patients with psoriasis." (PMID 38298734, 2024). "For example, OAS1, OAS2, OAS3, and IFI44L appear to be down-regulated by etanercept in responders to treatment for psoriasis." (PMID 30665420, 2019).
bladder urothelial carcinoma (3 papers, 2020 to 2023). "The genes co-expressed with OAS1, OAS2, OAS3, and OASL in Sanchez-Carbayo Bladder 2 dataset were identified using Oncomine in 48 normal samples, 81 filtrating bladder urothelial carcinoma tissues, and 28 superficial bladder cancer tissues." (PMID 36162993, 2022). "Until now, the roles of PDGFRA, OLR1, RAC3, PDF, OAS1, and SH3BP2 in bladder urothelial carcinoma remain largely unexplored." (PMID 32733809, 2020).
glioblastoma (3 papers, 2010 to 2025). The most malignant astrocytic tumor (WHO grade IV). "OAS1 is known to be upregulated and hypomethylated in glioblastoma and its silencing leads to an increase of temozolomide-sensitivity in vitro." (PMID 39915814, 2025).
glioma (3 papers, 2017 to 2025). A benign or malignant brain and spinal cord tumor that arises from glial cells (astrocytes, oligodendrocytes, ependymal cells). "We also validated the role of two upregulated and aggressiveness related RBPs (METTL1 and OAS1) in chemoresistance of LN229 glioma cells to temozolomide." (PMID 28035070, 2017). "Meanwhile, IRF7, MX2, and OAS1 are key mediators in immune regulatory pathways, and their overexpression may facilitate immune evasion in gliomas." (PMID 40365337, 2025). "We performed lentiviral shRNA mediated knockdown of METTL1 and OAS1 in LN229 glioma cells." (PMID 28035070, 2017). "We also validated the expression pattern of two upregulated (METTL1 and OAS1) and three downregulated genes (KHDRBS2, RANBP17 and ELAVL3) in glioma cell lines using qRT-PCR." (PMID 28035070, 2017).
liver disease (3 papers, 2008 to 2023). "The higher frequency of the “A” allele in rs2285934 (OAS-1; T > A) was shown to associate with severe liver disease in an HIV- and HCV-coinfected population of European descent in a cross-sectional study of 219 patients." (PMID 36833454, 2023). "In conclusion, Mx1 and OAS1-2 polymorphisms were associated with the severity of liver disease in HIV/HCV-coinfected patients, suggesting a significant role in the progression of hepatic fibrosis." (PMID 28139728, 2017). "The aim of this study was to analyze the association between Mx1 and OAS1-3 polymorphisms and severity of liver disease in HIV/HCV coinfected patients." (PMID 28139728, 2017). "In conclusion, Mx1 and OAS1-2 polymorphisms were associated with the severity of liver disease in patients coinfected with HIV and HCV, suggesting that these polymorphisms might play a significant role in the progression of hepatic fibrosis." (PMID 28139728, 2017). "The presence of Mx1 and OAS1-3 polymorphisms may be related to have moderate or significant liver disease." (PMID 28139728, 2017). "The aim was to analyze the association between 2′5′oligoadenylate synthetase 1,2 and 3 (OAS1-3) and myxovirus resistance proteins 1 (Mx1) polymorphisms and severity of liver disease in human immunodeficiency virus (HIV)/hepatitis C virus (HCV) coinfected patients." (PMID 28139728, 2017). "In our study, OAS1-3 polymorphisms were related to lower likelihood of having significant liver disease (A ≥ 2 and/or F ≥ 2), indicating that the A-allele conferred a protective effect with respect to liver disease progression." (PMID 28139728, 2017). "Thus, Mx1 and OAS1-2 polymorphisms might play a role in developing of liver disease in HIV/HCV-coinfected patients." (PMID 28139728, 2017). "In this way, OAS1 rs2285934 and OAS2 rs1293762 polymorphisms could increase expression of OAS1 and OAS2, improving the control of HCV, and might therefore be related to the decrease of sustained inflammation and progression of liver disease." (PMID 28139728, 2017). "The genetic variation observed within the OAS-1 gene region is considered to have a significant impact on the effectiveness of the OAS–RNase-L pathway, which might be a predictor for the advancement of liver disease in HCV infection." (PMID 36833454, 2023).
ovarian carcinoma (3 papers, 2021 to 2023). A malignant neoplasm originating from the surface ovarian epithelium. "(H, I) Immunohistochemical analysis of IL20RA, p-STAT3, OAS1, and IL-18 in human primary ovarian cancer tissues (Pri) and paired peritoneal metastatic nodules (Met) (H) and quantification (I)." (PMID 34114949, 2021). "Whether OAS1 has an impact on ovarian cancer is still to be elucidated." (PMID 38012143, 2023).
pancreatic adenocarcinoma (3 papers, 2022 to 2023). "Results showed that OAS1 expression was associated with several tumor pathologic stage, including BLCA, LUAD, PAAD (Pancreatic adenocarcinoma) and SKCM (Skin Cutaneous Melanoma)." (PMID 37746262, 2023). "In Logsdon Pancreas and Iacobuzio-Donahue Pancreas 2 datasets, OAS1 was 3.173 and 5.530 times higher in pancreatic adenocarcinoma compared with normal tissues." (PMID 35719943, 2022). "We applied bioinformatics method to analyze the relationship between OAS1 and clinical information and overall survival (OS) of pancreatic adenocarcinoma (PAAD)." (PMID 35898870, 2022).
Rotavirus infection (3 papers, 2017 to 2022). Infection with any of the rotaviruses. "Of interest, several IFN inducible genes (OAS1, MX1, IL18, IITP3, TAP1, and RSAD2) as well as several cytokines and chemokines (CCL5, CXCL10, CXCL11, IL8, and CCL15) were upregulated by rotavirus infection." (PMID 28210256, 2017). "Of note, OAS1 was not modified by rotavirus infection in any of the time points evaluated." (PMID 34163470, 2021).
systemic sclerosis (3 papers, 2015 to 2023). A chronic disorder, possibly autoimmune, marked by excessive production of collagen which results in hardening and thickening of body tissues. "The expression levels of interferon-regulated genes (OAS1 and IFI44) were found to be positively correlated with progressive lung fibrosis in patients with systemic sclerosis (SSc)–related interstitial lung disease (ILD)." (PMID 36061178, 2022).
AIDS (2 papers, 2019 to 2025). A syndrome resulting from the acquired deficiency of cellular immunity caused by the human immunodeficiency virus (HIV). "The analysis showed that individuals with the GA genotype of OAS1 rs1131454 were associated with a later AIDS clinical stage compared to those with the AA genotype (p = 0.013, OR = 1.697, 95% CI 1.117–2.577)." (PMID 40331958, 2025). "In addition, our study identified that individuals with the GA genotype at OAS1 rs1131454 were associated with a later clinical stage of AIDS compared to those with the AA genotype." (PMID 40331958, 2025). "Previous research suggested that OAS1 was significantly upregulated in people with AIDS with high viral loads compared to those with low viral loads, implying that increased OAS1 expression may contribute to an excessive immune inflammatory response and the progression of AIDS." (PMID 40331958, 2025). "Three SNPs (OAS1 rs1131454, NLRP3 rs10754558, and MAVS rs867335) were found to be related to the clinical staging of AIDS." (PMID 40331958, 2025).
angina (2 papers, 2022 to 2025). "In addition to its association with CRC and colon polyps, OAS1 was also significantly associated in the multi-trait analysis of CRC and angina pectoris, highlighting a possible link between immune system regulation, chronic inflammation, and cardiovascular health." (PMID 40303978, 2025). "Similarly, OAS1 was significantly associated with CRC and angina pectoris." (PMID 40303978, 2025).
Ebola (2 papers, 2016 to 2024). "OAS1 is activated upon recognizing double-stranded RNA (dsRNA) from viruses, including Ebola, leading to the synthesis of 2′-5′-linked oligoadenylates (2-5A)." (PMID 39282474, 2024).
encephalitis (2 papers, 2024 to 2025). An acute inflammatory process affecting the brain parenchyma. "In this species, increased susceptibility to encephalitis is associated with a genetic variation in a gene that codes for 2′-5′-oligoadenylate synthetase 1 (OAS1)." (PMID 40266979, 2025). "Regarding a genetic basis for WNV susceptibility, genetic variation in the regulatory region of an IFN-induced gene 2′-5′-oligoadenylate synthetase 1 (OAS1) has been related to increased susceptibility to encephalitis." (PMID 38793662, 2024). "Variation within a single SNP of the OAS1 gene has been strongly associated (OR = 9.79) with increased susceptibility to encephalitis and paralysis induced by WNV infection." (PMID 38793662, 2024).
Hepatic fibrosis (2 papers, 2017 to 2022). The presence of excessive fibrous connective tissue in the liver. "Single nucleotide polymorphisms in OAS1 are associated with susceptibility to chronic HCV infection, progression of hepatic fibrosis, hepatic necroinflammatory activity grade, and development of HCC." (PMID 39132059, 2022).
Hepatitis C (2 papers, 2009 to 2016). "For Hepatitis C, a relative of WNV also in the flavivirus family, a polymorphism in the 3′-untranslated region of OAS1 has been associated with persistent infection." (PMID 19247438, 2009). "Strikingly, West Nile, hepatitis C, and TBE are all members of the Flaviviridae family, suggesting that Flaviviruses might have been the main drivers of selection in OAS1." (PMID 27899133, 2016).
liver cancer (2 papers, 2022 to 2023). An epithelial or non-epithelial malignant neoplasm that arises from the liver. "Additionally, expression of OAS1 was lower in liver cancer patients with Neanderthal introgression (median CPM = 22.6) compared to liver cancer patients without introgression (median CPM = 32.3)." (PMID 36503519, 2022).
measles (2 papers, 2014 to 2022). A highly contagious viral infection caused by the measles virus. "An association was found with the OAS1 SNP rs10774671 and the response to measles vaccination in an African-American population." (PMID 25205466, 2014). "It seems as if OAS1 gene polymorphism might also be involved in the mechanism underlying the heterogeneous immune response to rubella and measles vaccinations." (PMID 25205466, 2014).
pulmonary alveolar proteinosis (2 papers, 2021 to 2023). A rare lung disorder characterized by the filling of the pulmonary alveoli with proteinaceous material which stains positive with periodic acid-Schiff stain. "Patients with OAS1 deficiency show hypogammaglobulinemia and pulmonary alveolar proteinosis (PAP) from infancy with defects in B cells and monocytes." (PMID 33766139, 2021).
respiratory infection (2 papers, 2018 to 2020). "In addition, OAS1 polymorphisms were reported to be associated with respiratory infection." (PMID 30497421, 2018).
West-Nile encephalitis (2 papers, 2010 to 2011). "We report associations of SNPs in the equine OAS1 gene with susceptibility to West Nile encephalitis." (PMID 20479874, 2010). "With naturally occurring susceptible and resistant sub-populations to lethal West Nile encephalitis, we undertook a case-control association study to investigate whether, similar to humans (OAS1) and mice (Oas1b), equine OAS1 plays a role in resistance to severe WNV infection." (PMID 20479874, 2010).